AFP (alpha fetoprotein)
Diseases named in the same sentence as AFP in open-access papers (continued):
Sharing a sentence is not in itself a finding about the gene and the disease.
hepatocellular carcinoma (continued). "A recent study from the US showed a decreasing trend in the elevated serum alpha-fetoprotein (AFP) level (i.e., ≥20 ng/mL) in hepatocellular carcinoma (HCC) patients at the time of diagnosis." (PMID 36831565, 2023). "Alpha fetoprotein (AFP) is the most important used and accepted serum predictive biomarker of hepatocellular carcinoma (HCC), with 20 ng/mL for HCC screening and diagnosis or 200 and/or 400 ng/mL for treatment stratification." (PMID 37630022, 2023). "NTN4: netrin-4; HCC: hepatocellular carcinoma; AFP: alpha-fetoprotein; PVI: portal vein invasion; IQR: interquartile range; p-value < 0.05 is statistically significant; * metastasis (intrahepatic and extrahepatic)." (PMID 37736464, 2023). "Differentiation diagnosis of hepatoid yolk sac tumor is required to clinically distinguish ovarian cancer from hepatocellular carcinoma, which is defined by the expression of broad-spectrum cytokeratins, AFP, and hepatocellular antigens with the absence of sex cord and germ cell markers." (PMID 36456989, 2022). "HBsAg, hepatitis B virus surface antigen; anti-HCV, antibody against hepatitis C virus; AST, aspartate transaminase; ALT, alanine transaminase; AFP, alpha-fetoprotein; WBC, white blood cell; BD, bone density; HU, Hounsfield unit; HCC, hepatocellular carcinoma." (PMID 36233438, 2022). "For example, in hepatocellular carcinoma, PNCK was highly expressed in the tumor as compared to the nontumor samples at both mRNA and protein levels; it is related to poorer prognosis, higher Edmondson grade, higher AFP levels, microvascular invasion, and intrahepatic metastasis." (PMID 35535310, 2022). "The InP/ZnSe/ZnS//ZnS QDs probes are prepared by coupling the alpha‐fetoprotein (AFP, serum markers of hepatocellular carcinoma [HCC]) antibody to quantify AFP antigen by using the QDs‐based fluorescence‐linked immunosorbent assay (QDs‐FLISA)." (PMID 37325608, 2022). "Emerging evidence also suggests that specific SLiMs derived from or encompassing the alpha-fetoprotein (AFP), a well-known embryo-specific and cancer-related protein, may have antitumor effects in several types of cancer (BC, prostatic cancer, and hepatocellular carcinoma)." (PMID 36496998, 2022). "AFP-L3 is a glycoprotein mainly derived from hepatoma cells that is not affected by AFP level." (PMID 34846705, 2021). "The results showed that compared with other preparations, MPDA@SPIO/SA-PEI/AFP-Fth had better ability to enhance MRI contrast of T2-weighted images in tumor region, and could be used as an effective MRI contrast agent for early detection of hepatocellular carcinoma (HCC)." (PMID 34819084, 2021). "Hepatocellular carcinoma (HCC) factors, especially maximum tumor diameter (MTD), tumor multifocality, portal vein thrombosis (PVT), and serum alpha-fetoprotein (AFP), influence survival." (PMID 33546234, 2021). "To determine whether HBx promotes the development of hepatoma through inhibiting the downregulation of AFP by HBP1, we overexpressed HBP1 with or without HBx in HepG2 cells." (PMID 33794968, 2021). "This is referred to as AFP-negative hepatocellular carcinoma (AFP-NHCC)." (PMID 32190001, 2020). "This study aimed to comprehensively assess the diagnostic value of fibrinogen to prealbumin ratio (FPR) and gamma-glutamyl transpeptidase to platelet ratio (GPR) as single markers or in combination in patients with alpha-fetoprotein-negative (AFP-negative) hepatocellular carcinoma (HCC)." (PMID 32190001, 2020). "New blood biomarkers with potential value for AFP-negative hepatocellular carcinoma diagnosis." (PMID 32923383, 2020). "On the contrary, in hepatocellular carcinoma (HCC) cells, the induction of the PI3K/Akt/mTOR pathway by α-fetoprotein (AFP) resulted in reduced cell autophagy and more malignant behavior." (PMID 30609663, 2019). "Introduction: serum alpha-fetoprotein (AFP) was routinely employed as a tumor marker for screening, diagnosis, and treatment follow-up of hepatocellular carcinoma (HCC)." (PMID 31635078, 2019).
hepatocellular carcinoma (continued). "Methods: between 2005 and 2015, patients with hepatocellular carcinoma who were treated with hepatectomy in Chang Gung Memorial Hospital Linkou branch were divided into two groups according to their preoperative serum AFP level (<15 ng/mL: NHCC; ≥15 ng/mL: abnormal AFP HCC (A-HCC))." (PMID 31635078, 2019). "Most prominently, the level of core fucosylation of N-glycan in alpha-fetoprotein (AFP) increases in hepatocellular carcinomas (HCC) and carcinoma metastatic to the liver, but not in benign liver diseases, such as acute viral hepatitis, chronic hepatitis, or liver cirrhosis." (PMID 29773815, 2018). "Similar results were also observed in patients with a normal serum AFP level (< 20 μg/L) and small hepatocellular carcinoma (SHCC, the diameter of HCC ≤ 5 cm)." (PMID 30100986, 2018). "Notably, serum MK had an outstanding performance in differentiating alpha-fetoprotein negative hepatocellular carcinoma from controls." (PMID 30200153, 2018). "Conclusively, HAS may be misdiagnosed as hepatocellular carcinoma; therefore, it should be considered in the differential diagnosis of multiple hepatic nodules with high AFP and no history of hepatitis, liver fibrosis or cirrhosis." (PMID 29034239, 2017). "The expression of SART3 was observed even in the hepatoma cell lines not expressing AFP (HLF, HLE)." (PMID 28114424, 2017). "In this study, we selected two distinctive markers of HCC, hepatocellular carcinoma monoclonal antibody (CHALV1) and α-fetoprotein (AFP)." (PMID 27756242, 2016). "The role of serum alpha-fetoprotein (AFP) levels in the surveillance and diagnosis of hepatocellular carcinoma (HCC) is controversial." (PMID 27304617, 2016). "However, accepted unique serological biomarker for gastric cancer, like as Alpha-fetoprotein (AFP) for hepatocellular carcinoma (HCC), remains absent." (PMID 26659608, 2015). "By using rescectd hepatocellular carcinoma (HCC) tissues, immunohistochemical analysis revealed NCL overexpression was correlated with tumour grades, vascular invasion, serum alpha-fetoprotein levels and the poor survival in HCC patients." (PMID 25938538, 2015). "This is the first report of a case with AFP-negative, differentiated hepatocellular carcinoma metastasis to the abdominal wall within a pre-existing subcutaneous lipoma since childhood after antiandrogen therapy with leuprorelin and buserelin acetate for prostate cancer without seeding." (PMID 22647077, 2012). "Final diagnostic evaluation, including ultrasound-guided FNAB of the liver mass and magnetic resonance imaging, resulted in the diagnosis of a multilocular, well-differentiated and AFP-negative hepatocellular carcinoma in liver segments II/III, VI, and VIII in April 2010." (PMID 22647077, 2012). "However, he reported observation of primary AFP-negative gastric carcinomas with characteristic histologic features mimicking hepatocellular carcinoma." (PMID 21592404, 2011). "The Con A-reactive and LCA-nonreactive species of AFP from patients with hepatocellular carcinoma contained a biantennary sugar chain, and the Con A-reactive and LCA-reactive species had a biantennary one with a fucose residue at the innermost N-acetylglucosamine residue." (PMID 7679920, 1993). "Additionally, alpha-fetoprotein (AFP) and alpha-fetoprotein agglutination reaction have been utilized for diagnosing and predicting the prognosis of hepatocellular carcinoma (HCC)." (PMID 40458727, 2025). "Finally, viral serology was negative for hepatitis A, B, and C, and the tumor marker for alpha-fetoprotein (AFP) was negative, making viral hepatitis and hepatocellular carcinoma less likely as underlying etiologies for her decompensation and taste disturbance." (PMID 41523421, 2025). "To test the performance in real samples, we collected the clinical serum samples of hepatocellular carcinoma (HCC) and non-HCC patients to detect AFP using AA-AuNP LFIAs." (PMID 38985882, 2024).
hepatocellular carcinoma (continued). "This study aimed to investigate the diagnostic value of stress-induced phosphoprotein 1 (STIP1) in serum for hepatocellular carcinoma (HCC) and alpha-fetoprotein (AFP)–negative HCC (ANHC)." (PMID 38780206, 2024). "The effectiveness of AFP in the early detection of HCC is limited, as most patients with early-stage hepatocellular carcinoma do not exhibit AFP seropositivity." (PMID 39200161, 2024). "For example, while AFP is often upregulated in cases of hepatocellular carcinoma (HCC), this is not universally true." (PMID 37122733, 2023). "Early diagnosis for α-fetoprotein (AFP) negative hepatocellular carcinoma (HCC) remains a critical problem." (PMID 36845695, 2023). "This study aimed to establish a simple prognostic scoring model based on tumor burden score (TBS) and PIVKA‐II to predict long‐term outcomes of α‐fetoprotein (AFP)‐negative hepatocellular carcinoma (HCC) patients." (PMID 38130028, 2023). "However, AFP was not secreted by all hepatoma cells, and it might also increase in some patients with cirrhosis or hepatitis." (PMID 35729579, 2022). "The level of alpha-fetoprotein (AFP) in patients with non-hepatitis B/non-C hepatocellular carcinoma (NBNC-HCC) was positively correlated with that of lncRNA TUG1, and the prognosis was poor." (PMID 34039257, 2021). "In addition, the RNA-seq data and clinical information of The Cancer Genome Atlas Liver Hepatocellular Carcinoma were collected to analyze the predictive values of AFP and ICAM-1 in the diagnosis, prognosis and immunotherapy of HCC." (PMID 34696675, 2021). "The diagnosis of AFP (alpha-fetoprotein)-negative HCC (hepatocellular carcinoma) mostly relies on imaging and pathological examinations, and it lacks valuable and practical markers." (PMID 33889548, 2021). "However, elevated AFP is not unique to hepatocellular carcinoma." (PMID 33854614, 2021). "Hepatocellular carcinoma (HCC) biomarkers are limited, as even the best studied, alpha-fetoprotein (AFP), is elevated in no more than 50% of HCC patients." (PMID 34540270, 2021). "Alpha-fetoprotein (AFP) and Protein Induced by Vitamin K Absence or Antagonist-II (PIVKA-II) have been proved to be efficient biomarkers for hepatitis B virus (HBV)-related hepatocellular carcinoma (HCC)." (PMID 32782270, 2020). "Alpha‐fetoprotein (AFP), routinely used for diagnosis of hepatocellular carcinoma (HCC), is limited with relatively low sensitivity and high false positivity in HBV‐related HCC (HBV‐HCC)." (PMID 32150664, 2020). "We have recently identified a panel of mouse TCRs specific for the HLA-A0201/alpha fetoprotein epitope (AFP158) complex and have shown that human T cells engineered with these TCR genes (TCR-Ts) can eradicate hepatocellular carcinoma (HCC) xenografts in NSG mice." (PMID 32395117, 2020). "Biannual ultrasound (US)—with or without alpha-fetoprotein (AFP)—is recommended by current guidelines for the surveillance of hepatocellular carcinoma (HCC)." (PMID 30249190, 2018). "Gastric hepatoid adenocarcinoma (GHA) was defined as a special subtype of primary gastric adenocarcinoma characterized by the histologic structures of “hepatocellular carcinoma- (HCC-) like differentiation” with or without excessive production of AFP." (PMID 29434637, 2017). "The aims of the study were to elucidate the clinical characteristics of patients who developed hepatocellular carcinoma (HCC) related to persistent HBV infection since childhood and to investigate usefulness of assessing alpha‐fetoprotein (AFP) in this population." (PMID 27748053, 2016).
hepatocellular carcinoma (continued). "We report a new biomarker of hepatocarcinoma, vasorin (VASN), screened by a subtractive EMSA-SELEX strategy from AFP negative serum of hepatocellular carcinoma (HCC) patients with extrahepatic metastases." (PMID 25826090, 2015). "The human AFP-promoter in combination with the hCMV enhancer element was demonstrated to be a valuable tissue-specific promoter for targeting hepatocellular carcinomas with non-viral gene delivery system, and tissue specific replication could be shown in vitro with the muscle specific SM22 promoter." (PMID 23734827, 2013). "The AFP isofoms we detected are similar to that reported previously in hepatocellular carcinoma (HCC) and nonseminomatous germ cell tumors (NSGCTs) patients." (PMID 20609214, 2010). "We examined the expression of the midkine (MK) and α-fetoprotein (AFP) genes in 15 paired human specimens obtained from hepatocellular carcinoma (HCC) and the corresponding noncancerous regions of the same patients." (PMID 12966430, 2003). "Alpha-fetoprotein (AFP) is widely used as a serological marker in the diagnosis of hepatocellular carcinoma (HCC) and non-seminomatous germ cell tumours (NSGCT)." (PMID 11044358, 2000). "Although estimation of serum alpha-fetoprotein (AFP) is widely used in the diagnosis of hepatocellular carcinoma (HCC) and non-seminomatous germ cell tumours (NSGCT), the clinical usefulness of this test is limited by a low specificity." (PMID 10584881, 1999). "Unlike primary hepatocellular carcinoma, most PHO patients present with normal serum AFP levels, with only two individuals demonstrating an increase." (PMID 41479782, 2025). "Alpha-fetoprotein (AFP) is an important biomarker used to diagnose hepatocellular carcinoma (HCC), but some patients with HCC may still test negative for AFP." (PMID 40308592, 2025). "AFP: Alpha-fetoprotein, ALT: Alanine aminotransferase, AST: Aspartate aminotransferase, INR: International normalized ratio, BCLC: Barcelona Clinic Liver Cancer staging system, FIB-4: Fibrosis-4 index, HCC: Hepatocellular carcinoma, HCV: Hepatitis C virus, and FIB4: Fibrosis-4 score." (PMID 41326479, 2025). "The utility of pre- and post-operative alpha-fetoprotein (AFP) and des-gamma (γ)-carboxy prothrombin (DCP) expression patterns and their dynamic changes as predictors of the outcome of hepatic resection for hepatocellular carcinoma (HCC) has yet to be well elucidated." (PMID 38903723, 2024). "Alpha-fetoprotein (AFP) is a biomarker used in clinical management of hepatocellular carcinoma (HCC), however, approximately 40% of HCC patients do not present with elevated serum AFP levels." (PMID 35461226, 2022). "If the FIB-4 index and AFP are high, it has been reported that HCC will develop in 14.6% of cases within 2 years in patients with no history of hepatocellular carcinoma." (PMID 33278003, 2021). "Gamma-glutamyltransferase (GGT) is involved in tumor development and progression, but its prognostic value in α-fetoprotein- (AFP-) negative (AFP < 25 ng/mL) hepatocellular carcinoma (HCC) patients remains unknown." (PMID 32695241, 2020). "α-Fetoprotein (AFP) is considered a good target for immunotherapy strategies against hepatocellular carcinoma (HCC); however, no immunodominant AFP-derived MHC class II-restricted helper T-lymphocyte (HTL) epitope has been reported." (PMID 32132566, 2020). "Alpha‐fetoprotein (AFP) has received extensive attention in the differential diagnosis of hepatocellular carcinoma (HCC), especially for AFP‐negative HCC (AFP‐NHCC)." (PMID 31693242, 2020). "Moreover, compared with alpha-fetoprotein (AFP), OPN as a chemoattractant for macrophages and neutrophils during injury is considered to be a better prognostic marker for early hepatocellular carcinoma (HCC)." (PMID 32104688, 2020).
hepatocellular carcinoma (continued). "mRNAs of hepatocyte/hepatoma markers, such as albumin, ApoA1, CYP3A4, and AFP, were detectable in KH and Huh-7.5 cells, but not in A549 cells, indicating that KH cells, similar to Huh-7.5 cells, are derived from hepatocyte/hepatoma cells." (PMID 31138826, 2019). "Although alpha-fetoprotein (AFP) is a widely used tumor marker in hepatocellular carcinoma (HCC), 40% of newly diagnosed patients do not have an elevated AFP level." (PMID 31915469, 2019). "Some serum markers, such as alpha-fetoprotein (AFP) and alkaline phosphatase (ALP or AKP), are widely used in clinical practice, yet they lacked adequate sensitivity and specificity for the hepatic carcinoma with metastasis." (PMID 28427195, 2017). "To detect the targeting of 131I-antiAFPMcAb-GCV-BSA-NPs to hepatoma, we compared the uptake and the retention of 131I-antiAFPMcAb-GCV-BSA-NPs in AFP-positive HepG2 cells with those in AFP-negative HEK293 cells in vitro." (PMID 26981334, 2016). "Interestingly, the expression level of α-fetoprotein (AFP), a putative hepatocellular carcinoma (HCC) marker, was significantly higher in tumors compared to normal liver tissue (p < 0.05)." (PMID 25623590, 2015). "For example, elevation of serum alpha-fetoprotein (AFP), a common marker for hepatocellular carcinoma (HCC), also occurs in non-HCC conditions such as pregnancy." (PMID 24872809, 2014). "Elevated serum alpha-fetoprotein (AFP) is not only a diagnostic marker for hepatocellular carcinoma (HCC), but is also a risk factor for HCC in chronic hepatitis C patients who do not have HCC." (PMID 22681639, 2012). "Recent research favors the circulating hepatoma-specific AFP subfraction AFP-L3 and DCP over AFP alone in differentiating HCC from nonmalignant hepatopathy and detecting small HCC." (PMID 22655201, 2012). "However, in the HCC patient population, AFP-negative hepatocellular carcinoma (ANHC), i.e., AFP < 20 ng/mL at initial diagnosis, is an important type that causes many patients to lose early diagnosis and treatment and accounts for approximately 30-40% of patients." (PMID 38438972, 2024). "The nomogram based on clinical and serum parameters could be used as a marker for the diagnosis of AFP-negative HCC, providing an objective basis for the early diagnosis and individualized treatment of hepatocellular carcinoma patients." (PMID 36890811, 2023). "In the present study, we observed that serum values of five biomarkers (namely, AFP, PIVKA-II, GPC-3, adiponectin and IL-6) were significantly different between patients with and without hepatocellular carcinoma; the best accuracy for the detection of tumor was achieved by PIVKA-II." (PMID 34064999, 2021). "The virtually negative AFP does not rule out a YST, while expression of glypican-3 can be found in various somatic tumor types such as hepatocellular carcinoma, hepatoid carcinoma, neuroendocrine carcinoma, thyroid carcinomas, lung carcinoma, liposarcoma, and melanoma." (PMID 32774158, 2020). "However, AFP is not unique to HAL and is more commonly found in hepatocellular carcinoma, cholangiocarcinoma and teratomatous germ cell tumors." (PMID 24959228, 2014). "Furthermore, Survivin plasma levels were evaluated compared to alpha fetoprotein (AFP) in patients with chronic hepatitis C viral infection (HCV) with and without hepatocellular carcinoma (HCC)." (PMID 23091600, 2012). "Stains for hepatocellular carcinoma (HCC), including Hep-Par1 and AFP, are negative." (PMID 17626622, 2007). "Additionally, elevated alpha-fetoprotein (AFP) levels may be observed and can aid in the diagnosis of hepatocellular carcinoma, although this is not universally present." (PMID 40709997, 2025). "AFP, alpha‐fetoprotein; CHB, chronic hepatitis B; CRC, colorectal cancer; ESCC, esophageal cancer; GC, gastric cancer; HCC, hepatocellular carcinoma; IA, inapplicable; NA, not available; NC, normal control; SD, standard deviation." (PMID 36587394, 2023).
hepatocellular carcinoma (continued). "However, up to 30–40% of patients with HCC exhibit low AFP levels; this condition is defined as alpha-fetoprotein-negative hepatocellular carcinoma (AFPNHCC) when AFP levels are equal to or less than 20 ng/ml6." (PMID 38730095, 2024).